CXCL12 (C-X-C motif chemokine ligand 12)
Diseases named in the same sentence as CXCL12 in open-access papers (continued):
Sharing a sentence is not in itself a finding about the gene and the disease.
prostate carcinoma (continued). "Prostate cancer cells can also release PKM2-carrying EVs to educate the bone marrow environment into a metastatic niche by transferring PKM2 to bone marrow stromal cells with subsequent upregulation of CXCL12 cytokine." (PMID 40089067, 2025). "Notably, prostate cancer-derived exosomes containing pyruvate kinase M2 (PKM2) upregulate CXCL12 in bone marrow MSCs, which enhances tumor cell seeding and proliferation in the bone marrow." (PMID 40606222, 2025). "Prostate cancer cells migrated from a primary tumor site to a bone chip, guided by CXCL12." (PMID 40606222, 2025). "For example, prostate cancer-associated fibroblasts promote immunosuppression on T cells by the release of transforming growth factor-β60 or by recruiting suppressive myeloid cells through the CCL2 and CXCL12 pathways." (PMID 39633050, 2025). "CXCL12/CXCR4 pathway biological axis is an important regulator of the spread of prostate cancer." (PMID 41347146, 2025). "Notably, research on prostate cancer has identified that CXCL12 secreted by stromal cells can stimulate the invasive characteristics of prostate cancer cells, potentially playing a significant role in tumor progression associated with obesity." (PMID 38920657, 2024). "In addition, CXCL12 is another important angiogenesis-promoting factor in lung cancer, prostate cancer and melanoma." (PMID 39075612, 2024). "CXCR4/CXCL12 also plays a crucial role in bone metastasis of prostate cancer." (PMID 38464516, 2024). "In addition to CXCL12, other studies have also implicated cytokine CCL20 and its receptor CCR6 for their involvement in prostate cancer bone metastasis." (PMID 36836690, 2023). "In addition, higher expression of CXCL12 leads to the increased adhesion of prostate cancer cells in the endothelial cell monolayer and immobilized fibronectin, laminin, collagen, and osteosarcoma cells due to the upregulation of α5 and β3 integrins." (PMID 36826044, 2023). "Their study revealed that Luteolin, Ellagic Acid, and Punicic Acid inhibited growth and metastasis in the C-X-C motif chemokine ligand 12 (CXCL12)/C-X-C chemokine receptor type 4 (CXCR4) axis in human prostate cancer xenograft tumors in severe combined immunodeficiency mice." (PMID 36992138, 2023). "CXCL12/CXCR4 signaling promote initial establishment of prostate cancer colonization in bone microenvironment by actively competing with osteoblastic niche and these interactions along with cross talk with bone microenvironment factors promoting bone tumor growth." (PMID 37996444, 2023). "In in vitro studies using prostate cancer cell lines, rosiglitazone might inhibit the migration and invasion of prostate cancer cells through its inhibitory effect on the CXCR4/CXCL12 axis and downregulation of vascular endothelial growth factor." (PMID 37560306, 2023). "A prior study reported that PKM2 transferred via endosomes increases the expression of CXCL12 in recipient prostate cancer cells in bone marrow, which could initiate a feed-forward pathway, allowing for disseminated tumor cells to survive and proliferate." (PMID 35681470, 2022). "Interestingly, CXCL12 has also been shown to facilitate adhesion of prostate cancer cells expressing CXC receptor 4 (CXCR4) to endothelial cells and ECM proteins via α5β3 integrin to facilitate tumor dissemination." (PMID 36671452, 2022). "Bone-derived CAFs express CXCL12 which directly stimulates the CXCR4 receptor on the surface of prostate cancer cells to elicit a protective effect from chemotherapy, as well as promoting metastatic progression and attracting inflammatory immune cells to the TME." (PMID 36671452, 2022). "For example, many studies reported that inhibiting the GPR30 receptor on the cell surface of CAFs can inhibit the level of CXCL12 secreted by CAFs, reduce the recruitment of macrophages and M2-type polarization, thereby impairing the ability of prostate cancer cells to metastasize and invade." (PMID 35853880, 2022).
prostate carcinoma (continued). "Specifically, CXCL12/CXCR4 signaling axis in prostate cancer bone metastasis (the main site of prostate cancer dissemination) participates in the formation of the endosteal niche, and blocking this axis compromises initial establishment of tumors in the bone microenvironment." (PMID 33572160, 2021). "Therefore, CXCL12 in the microenvironment of prostate cancer can recruit white blood cells expressing the corresponding receptor." (PMID 34659412, 2021). "Furthermore, the decreased secretion of CXCL12 by annexin knockout bone marrow stromal cells was reported as significantly reducing prostate cancer cell migration and binding." (PMID 32585812, 2020). "CXCL12 may also be involved in arrest of CTCs to endothelial cells as prostate cancer cells activation by CXCL12 promoted upregulation of cell surface adhesion molecules and enhanced bone metastasis." (PMID 32585812, 2020). "Despite the low levels of endogenous CXCR4 expression in LNCaP and DU-145 cells, it was found that CXCL12 facilitated increased adhesion of these prostate cancer cells to monolayers of endothelial cells and immobilized matrix through enhanced expression of α5 and β3 integrins." (PMID 32585812, 2020). "CXCL12/CXCR4 signalling activates MMP-9 expression in prostate cancer cells." (PMID 31718684, 2019). "This hypothesis is supported by preclinical models demonstrating recruitment of MSCs to prostate cancer promotes metastasis through a CXCL16/CXCL12-dependent mechanism." (PMID 28493842, 2017). "Moreover, CAFs drive SDF-1/CXCL12 production, which is also a chemoattractant of macrophages and promote M2 macrophage polarization in prostate cancer." (PMID 28467800, 2017). "T cells have also been shown to traffic to the BM efficiently via the CXCR4/CXCL12 axis in prostate cancer patients, which implies that adoptively transferred NK cells may also be able to traffic to the BM in leukemia patients." (PMID 28915651, 2017). "Drebrin is also upregulated in human prostate cancer cell lines and co-localizes with actin filaments and dynamic microtubules in filopodia of pseudopods of invading cells under a chemotactic gradient of the chemokine CXCL12." (PMID 28319065, 2017). "Prostate cancer proliferation and metastasis may also be stimulated by SDF-1 (CXCL12), CCL2 and other factors." (PMID 26317041, 2015). "Moreover, androgen-triggered motility of prostate-cancer cells depends on signaling by the CXCL12/CXCR7/CXCR4 axis." (PMID 25884570, 2015). "More importantly, CXCL11 and CXCL12 were able to attenuate the expression of endogenous ARGs, demonstrating crosstalk between chemokine/chemoreceptor pathways and AR-mediated gene expression programs in prostate-cancer cells." (PMID 25884570, 2015). "In addition to enhancing angiogenesis and lymphangiogenesis, Pim kinases are likely to promote metastatic prostate cancer growth by employing the CXCL12/CXCR4 chemokine pathway." (PMID 26075720, 2015). "In addition, Pim-1 has been shown to regulate the CXCR4/CXCL12 chemokine pathway, which plays an important role in migration and invasion of both leukemic and prostate cancer cells." (PMID 26075720, 2015). "The chemokine receptor CXCR4, a direct transcriptional target of KLF5, is subsequently activated and binding of its ligand CXCL12 (CXCL12, also known as SDF-1α) underlies the preferential chemotactic migration of prostate cancer cells to organ sites with elevated levels of CXCL12, for example bone." (PMID 24429391, 2014). "Furthermore, CXCL8 signaling also increased the expression of CXCR4 and CXCR7 (the receptors mediating the biological activity of CXCL12) and CCR2 (a receptor activated by the ligand CCL2) in both PTEN-expressing and PTEN-deficient prostate cancer cells." (PMID 24970800, 2014). "Our current findings propose that tumor-derived CXCL8, through the regulation of fibroblast-derived CXCL12 production, may drive immune evasion in prostate cancer." (PMID 24970800, 2014).
prostate carcinoma (continued). "The effects of CXCL12 on the expression and/or activity of integrins along with their repertoire on cell surfaces may affect prostate cancer cell adhesion and the manner in which these cells spread in microenvironments containing FN and COL." (PMID 25580125, 2014). "Thus, our experiments indicate that CXCL8 and CXCL12 signaling co-operate to accelerate the migration of prostate cancer cells." (PMID 24970800, 2014). "Co-culture experiments were conducted to examine whether CXCL8-induced increases in stromal cell-derived CXCL12 expression could potentiate prostate cancer cell migration." (PMID 24970800, 2014). "Emerging data highlight the significance of chemokine (C-X-C motif) ligand 12/chemokine (C-X-C motif) receptor 4 (CXCL12/CXCR4) signaling axis in the chemoresistance of several malignancies, including prostate cancer (PCa); however, underlying mechanisms remain largely elusive." (PMID 25359780, 2014). "Therefore, the initial objective of this study was to establish the existence of interplay between tumor-derived CXCL8 from PTEN-deficient prostate cancer cells and the potentiation of stromal-derived CCL2 and CXCL12 expression and/or signaling." (PMID 24970800, 2014). "We hypothesize that loss of PTEN and subsequent activation of Akt, frequent occurrences in prostate cancer, regulate the CXCL12/CXCR4 signaling axis in tumor growth and bone metastasis." (PMID 23902739, 2013). "Moreover, a previous study demonstrated that the CXCR4/CXCL12 interaction activates PI3K/AKT signaling in prostate cancer cells." (PMID 22359577, 2012). "Treatment of prostate cancer cells with CXCL12 at a concentration of 100 ng/ml induced activation of the PI3K/AKT pathway (up to 1.5–2.0 fold increase in AKT phosphorylation in PC3 and DU145 cells, respectively), in addition to increasing the CD44+/CD133+ population for both PC3 and DU145 cells." (PMID 22359577, 2012). "However, little is known about the role of the CXCR4/CXCL12 signaling pathway in the maintenance of prostate cancer progenitors." (PMID 22359577, 2012). "CXCL12-dependent modulation of tumor cell proliferation and survival (under suboptimal conditions) has been observed in several tumor types, including ovarian carcinoma, small cell lung cancer and prostate cancer." (PMID 23249693, 2012). "CXCL12 can activate lymphocytes and take part in the metastasis of prostate cancer." (PMID 21448465, 2011). "We showed that CXCL12 is required for SLUG-mediated MMP9 expression in prostate cancer cells." (PMID 22074556, 2011). "Furthermore, we determined that forced expression of SLUG increased migration and invasion of human prostate cancer cells through activation of CXCR4/CXCL12 axis." (PMID 22074556, 2011). "CXCL12 expression was significantly higher in human prostate cancer tissue than hyperplastic prostate tissues, suggesting that CXCL12 has an autocrine regulatory role via its receptor CXCR4 in the regulation of prostate cancer cell migration, invasion, and metastasis." (PMID 22074556, 2011). "Thus, our data indicated that CXCL12 is critical for SLUG-mediated invasion of prostate cancer cells." (PMID 22074556, 2011). "Our findings suggest that CXCL12 is a therapeutic target for prostate cancer metastasis." (PMID 22074556, 2011). "Our data suggest that SLUG could positively regulate the CXCL12/CXCR4 signaling in prostate cancer cells, leading to cancer migration and invasion." (PMID 22074556, 2011). "Based upon these observations, we hypothesized that prostate cancer (CaP) cells may use the CXCL12/CXCR4 axis to home to bone marrow." (PMID 16859559, 2006). "However, short-term exposure of cancer cells to CXCL12 activates the affinity of prostate cancer cells for αvβ3 ligands in addition to increasing the level of receptor expression." (PMID 16859559, 2006).
prostate carcinoma (continued). "Finally, CTCE-9908 is a CXCL12 analog that strongly blocks the CXCR4/CXCL12 axis, leading to reduced tumor growth and metastases in various preclinical models including osteosarcoma and melanoma, esophageal cancer, breast and prostate cancer." (PMID 40307933, 2025). "Indeed, CXCL12 can enhance the adhesion of prostate cancer cells with osteosarcoma cells." (PMID 33535458, 2021). "Furthermore, AKT could play a crucial role in the early phase of bone metastasis of breast and prostate cancer because the AKT signaling is strongly involved in different levels of the CXCL12/CXCR4 axis." (PMID 34064589, 2021). "Moreover, CXCL12 is expressed at high levels in bladder cancer, gastric cancer, hepatocellular carcinoma, prostate cancer, lung cancer, and many other human tumors." (PMID 33363463, 2020). "The elevated CXCL12 may be correlated with poor prognosis and aggressiveness of prostate cancer." (PMID 25580125, 2014). "Our study complements prior studies which have reported the significance of stromal-derived CXCL12 signaling in driving the invasion and metastasis of prostate cancers, and provides a more-detailed understanding of how stromal-derived chemokine signaling may be induced." (PMID 24970800, 2014). "Our studies show that CTCE-9908 is efficacious in inhibiting total tumor burden without significantly reducing primary tumor burden suggesting that targeting CXCL12/CXCR4 axis may be therapeutically beneficial for the management of prostate cancer patients undergoing chemo or radiation therapy." (PMID 24472670, 2014). "Contrasting findings of Wang and co-workers who demonstrated that expression of CXCR7 in a CXCR4 background in prostate cancer led to faster primary tumor growth suggest that growth regulating functions of CXCL12 may depend on tumor cell origin and on the tumor environment." (PMID 24040160, 2013). "Therefore, it would be worthwhile to use mouse models to test whether CXCL12 is a key mediator of SLUG-induced metastasis of prostate cancer in vivo." (PMID 22074556, 2011). "In prostate cancer with estrogen overexpression, recruitment and proliferation of TAMCs with an inflammatory cytokine profile was mediated by CAF-derived CXCL12, leading to a protumorigenic effect." (PMID 40805183, 2025). "DEU patterns were much more noticeable as compared to breast and prostate cancer, with SPP1 as well as its interacting partners S100A4 and CXCL12 showing significant differences in exon usage in tumor-affected samples." (PMID 39857756, 2025). "In the prostate cancer TME, macrophages primarily polarize toward the M1 state and utilize CXCL12/CXCR4 crosstalk to chemoattract peripheral CD8+ effector T cells, which target and kill cancer cells, thereby impeding tumor progression." (PMID 40698080, 2025). "For instance, downregulation of CXCR7 protein has been shown to increase migration in some settings, supporting a role for CXCR7 as a decoy receptor that sequesters CXCL12 and thereby counteracts CXCL12/CXCR4-mediated migration in prostate cancer." (PMID 41347146, 2025). "In prostate cancer, docetaxel-treated cells secrete CSF-1 to recruit TAMs, which then activate CXCR4 signaling via CXCL12 secretion, promoting tumor cell survival and resistance to chemotherapy." (PMID 40433363, 2025). "Studies have shown that prostate cancer cells transfer pyruvate kinase M2 (PKM2) to bone marrow stromal cells (BMSCs) through exosomes, upregulating CXCL12 production to “educate” the bone marrow microenvironment and create pre-metastatic niches." (PMID 41459253, 2025). "In the immune microenvironment of bone metastasis from prostate cancer, Tregs can translocate to the bone marrow through C-X-C chemokine receptor 4 (CXCR4)/C-X-C Motif Chemokine 12 (CXCL12)." (PMID 38464516, 2024). "Combined with its ligand CXCL12, CXCR4/CXCL12 axis increased the aggressiveness of PCa and enhanced the ability of prostate cancer cells to adhere to the extracellular matrix." (PMID 38800374, 2024).
prostate carcinoma (continued). "For example, CXCL12, or the stromal-derived factor 1 (SDF-1), is a CXC chemokine, and its receptor CXCR4 is reported to play a critical role in the spread of prostate cancer cells to the bone." (PMID 36826044, 2023). "Another study found that primary prostate cancer cells educate the bone marrow to promote bone metastasis through primary prostate cancer EV-mediated transfer of PKM2 into bone marrow mesenchymal cells and subsequent upregulation of CXCL12." (PMID 38037077, 2023). "In prostate cancer, estrogen-induced CAF-derived CXCL12 binds to CXCR4 and enhances mast cell proliferation, migration, and inflammatory cytokine secretion, thus exhibiting oncogenic effects." (PMID 37719863, 2023). "In terms of cancer metastasis, ROSI activates PPARγ and inhibits the activation of the PI3K-Akt pathway by inhibiting downregulation of CXCL12-induced migration and invasion on the CXCL12/CXCR4 axis in prostate cancer cell lines." (PMID 37251321, 2023). "Decreased CXCL12 expression inhibited the expression of MMP9 mediated by zinc-finger transcription factors and reduced the metastasis of prostate cancer cells." (PMID 37497001, 2023). "In prostate cancer, β-adrenoceptor signaling in osteoblasts promotes the secretion of CXCL12 and binding to CXCR4 on surface of prostate cancer cells resulting in increases bone metastasis formation." (PMID 34284799, 2021). "CD26/DPPIV cleaves and degrades CXCL12, and in vivo assay found that animals treated with a DPPIV inhibitor had increased prostate cancer cells in all tissues, especially in osseous tissues." (PMID 33777580, 2021). "Since CXCL12 is a classical ligand of CXCR4 and CSF-1/CSF-1R crosstalk from prostate cancer cells to recruited macrophages was previously identified, we proposed that the feedback crosstalk from macrophages to cancer cells is partly mediated by CXCL12/CXCR4." (PMID 34069563, 2021). "The CXCL12/CXCR4 axis was shown to be important for the homing of breast and prostate cancer cells to the bone in the early phases of bone metastasis." (PMID 34064589, 2021). "In prostate cancer, CAF-mediated CXCL12/CXCR4 axis induces the differentiation of monocytes and possibly M1 cells into pro-tumor M2 cells." (PMID 34447750, 2021). "Subsequently, the CXCL12/CXCR4 interaction drive the survival and adaptation to the requirements of the bone microenvironment after breast and prostate cancer colonized the bone marrow." (PMID 34064589, 2021). "On the other hand, most prostate cancer cells express elevated levels of CXCR4, which makes the CXCL12/CXCR4 axis more active in these cells." (PMID 33535458, 2021). "Alterations in the CXCL12/CXCR7 axis can influence tumor cell invasion and adhesion processes in prostate cancer, increasing the expression of CD44, and niche factors like VEGF, which suggests a role for CXCR7 in the CSC niche." (PMID 33530455, 2021). "Prostate cancer cells and α-SMA+ CAFs cooperatively recruited macrophages and polarized them to M2-like TAMs via CCL2, CXCL12, and IL-6, while recruited macrophages conferred malignant and activation phenotypes on cancer cells and CAFs, respectively." (PMID 33050237, 2020). "The overexpression of CXCR4 or CXCL12γ, an isoform of CXCL12 found in CD44+/CD133+ prostate CSCs, suggests that one mechanism by which the CXCR4/CXCL12 axis promotes metastasis in prostate cancer is the maintenance of stemness in CSCs." (PMID 31991604, 2020). "Expression of CXCL12 and CXCR4 are increased in prostate cancer, with high CXCR4 expression being an indicator for bone metastasis." (PMID 32585812, 2020). "Prostate cancer cells express high levels of CXCR4, which via a concentration gradient migrate by chemotaxis towards the high CXCL12 expressing bone tissues." (PMID 32585812, 2020). "Plerixafor inhibits tumor–stroma interactions through CXCL12/CXCR4 pathway, enhancing efficacy of docetaxel in prostate cancer." (PMID 32824865, 2020).